SNORD3D (small nucleolar RNA, C/D box 3D )
Synonyms: RNU3-4; U3-4
Gene: Small nucleolar RNA gene on chromosome 17 (19,112,420 to 19,112,636, reverse strand). Ensembl gene ENSG00000281000.
Gene Ontology:
Biological process: RNA processing
Cellular component: nucleolus
Homologues: Orthologues: chimpanzee U3 (93% identical), macaque U3 (90% identical), macaque U3 (89% identical). Paralogues in human: SNORD3E (81% identical), SNORD3P1 (80% identical), U3 (79% identical), SNORD3G (79% identical), U3 (78% identical), U3 (77% identical), SNORD3H (76% identical), U3 (76% identical), U3 (75% identical), U3 (74% identical), U3 (73% identical), U3 (72% identical), and 10 more.
Diseases named in the same sentence as SNORD3D in open-access papers:
SNORD3D is named in the same sentence as 3 diseases in open-access papers, as found by Europe PMC text mining. Sharing a sentence is not in itself a finding about the gene and the disease. The quoted sentences say what the papers report.
immune dysfunction (1 paper, 2022). "The dysregulation of U3 small nucleolar ribonucleoproteins genes (SNORD3B-1, SNORD3A, SNORD3B-2, SNORD3C, and SNORD3D) are related to age-related immune dysfunction, G0/G1 to S phase transition, oxidative-/ER-stress (23349890), and pathogenesis of AD." (PMID 35958988, 2022).
infection (1 paper, 2025). The state of being infected such as from the introduction of a foreign agent such as serum, vaccine, antigenic substance or organism. "SNORD3D also exhibited strong upregulation, suggesting potential modulation of small RNA processing during infection." (PMID 41477009, 2025).
SNORD3D also shares sentences with these, for which no sentence is quoted: breast carcinoma (1 paper).